LFNG (LFNG O-fucosylpeptide 3-beta-N-acetylglucosaminyltransferase)
Description:
Glycosyltransferase that initiates the elongation of O-linked fucose residues attached to EGF-like repeats in the extracellular domain of Notch molecules. Modulates NOTCH1 activity by modifying O-fucose residues at specific EGF-like domains resulting in inhibition of NOTCH1 activation by JAG1 and enhancement of NOTCH1 activation by DLL1 via an increase in its binding to DLL1 (By similarity). Decreases the binding of JAG1 to NOTCH2 but not that of DLL1. Essential mediator of somite segmentation and patterning (By similarity).
Synonyms: SCDO3
Tractability: Antibody: UniProt predicts a signal peptide or a membrane-spanning region.
Gene: Protein-coding gene on chromosome 7 (2,512,529 to 2,529,177, forward strand). Ensembl gene ENSG00000106003.
Subcellular location: Golgi apparatus; Golgi apparatus membrane
Subcellular location (Human Protein Atlas): Golgi apparatus; Nuclear membrane
Pathways (Reactome):
Developmental Biology: Nephron development; Somitogenesis
Disease: Defective LFNG causes SCDO3
Signal Transduction: Pre-NOTCH Processing in Golgi
Gene Ontology:
Molecular function: O-fucosylpeptide 3-beta-N-acetylglucosaminyltransferase activity; glycosyltransferase activity
Biological process: regulation of somitogenesis; animal organ morphogenesis; marginal zone B cell differentiation; negative regulation of Notch signaling pathway; regulation of Notch signaling pathway; somitogenesis; T cell differentiation; pattern specification process
Cellular component: extracellular vesicle; extracellular region; Golgi apparatus; Golgi membrane; membrane
Genetic constraint (gnomAD): Loss-of-function variants: 15 observed, 30.59 expected, observed/expected ratio (o/e) 0.49, 90% interval 0.33 to 0.75. The synonymous counts are far from expectation, so gnomAD's model fits this gene poorly and the ratio says little. Missense variants: 520 observed, 510.89 expected, observed/expected ratio (o/e) 1.02, 90% interval 0.95 to 1.09. Synonymous variants: 274 observed, 223.94 expected, observed/expected ratio (o/e) 1.22, 90% interval 1.11 to 1.35.
Homologues: Orthologues: macaque LFNG (97% identical), pig LFNG (93% identical), dog LFNG (92% identical), mouse Lfng (89% identical), rat Lfng (86% identical), rabbit LFNG (79% identical), tropical clawed frog lfng (65% identical), zebrafish lfng (63% identical), Drosophila melanogaster fng (37% identical). Paralogues in human: RFNG (53% identical), MFNG (50% identical), B3GLCT (20% identical).
Diseases named in the same sentence as LFNG in open-access papers:
LFNG is named in the same sentence as 32 diseases in open-access papers, as found by Europe PMC text mining. Sharing a sentence is not in itself a finding about the gene and the disease. The quoted sentences say what the papers report.
spondylocostal dysostosis (4 papers, 2020 to 2023). Spondylocostal dysplasia is a rare genetic disorder characterized by defects of the bones of the spine (vertebrae) and abnormalities of the ribs. "Similarly, the other genes associated with recessive spondylocostal dysostosis (MESP2, LFNG, and HES7) have been associated with regulating Notch-signaling activity during somitogenesis." (PMID 36506336, 2022).
breast carcinoma (3 papers, 2017 to 2022). "Higher expression of LFNG was correlated with better survival in breast cancer, while ST3GAL6 expression was correlated with poor survival." (PMID 36476410, 2022). "Four genes AQP1, LFNG, RASSF2 and WWP2 were reported to be associated with breast cancer." (PMID 31640538, 2019). "The study also evaluated the influence of the ADAM10, NOTCH1, NOTCH3, HES1, LFNG and PSEN1 genes on breast cancer recurrence." (PMID 27888801, 2017).
lung adenocarcinoma (2 papers, 2016 to 2023). A carcinoma that arises from the lung and is characterized by the presence of malignant glandular epithelial cells. "As a result, combinations of CDH3, LFNG, and PLAU were significantly associated with overall survival (log-rank test p-value: 2.376 × 10−5) compared to other protein combinations and cancers (e.g. hepatocellular carcinoma, colorectal adenocarcinoma, and lung adenocarcinoma)." (PMID 27869176, 2016).
Alzheimer disease (1 paper, 2024). A progressive, neurodegenerative disease characterized by loss of function and death of nerve cells in several areas of the brain leading to loss of cognitive function such as memory and language. "These categories include WNT (WNT1, WNT3A, WNT6, AXIN2, TNF2, MMP7), Alzheimer disease presenilin (WNT1, WNT3A, WNT6, MMP7), cadherin (WNT1, WNT3A, WNT6) and Notch (LFNG, HES1) signaling pathways." (PMID 38928376, 2024).
COVID-19 (1 paper, 2022). A disease caused by infection with severe acute respiratory syndrome coronavirus 2. "Among them, S100A9, AHNAK, and CX3CR1 have been reported as potential COVID-19 biomarkers previously, and the others (TRAF3IP3 and LFNG) are closely associated with the immune and virus-related signaling pathways." (PMID 35885892, 2022). "Notably, we identified two genes (TRAF3IP3 and LFNG) that have not been reported to be associated with COVID-19, which may be potential COVID-19 biomarkers or involved in the immune response to COVID-19." (PMID 35885892, 2022).
dementia (1 paper, 2024). Loss of intellectual abilities interfering with an individual's social and occupational functions. "The genes with much more significant association with clinical dementia, but not with AD diagnoses, include SLC46A1 and LFNG." (PMID 38343831, 2024).
Immune deficiency (1 paper, 2019). "Immune deficiency may be related to several genes, especially Platelet-derived growth factor alpha (PDGFalpha), caspase recruitment domain 11 (CARD11), N-acetylglucosaminyltransferase lunatic fringe (LFNG), MafK, and G protein-coupled estrogen receptor 1 (GPER-1)." (PMID 31474980, 2019).
melanoma (1 paper, 2018). A malignant, usually aggressive tumor composed of atypical, neoplastic melanocytes. "We focused on lunatic fringe (LFNG) that encodes for a glycosylating enzyme (O‐fucosylpeptide 3‐beta‐N‐acetylglucosaminyltransferase) that regulates NOTCH signalling, and show an important role for this gene in controlling melanoma metastasis." (PMID 29193607, 2018).
mesothelioma (1 paper, 2023). A usually malignant and aggressive neoplasm of the mesothelium which is often associated with exposure to asbestos. "Our results showed that high expression of LFNG was associated with poor prognosis in patients with mesothelioma (MESO), uveal melanoma (UVM), LGG, and PAAD." (PMID 37932706, 2023).
periodontitis (1 paper, 2024). An acute or chronic inflammatory process that affects the tissues that surround and support the teeth. "The allele frequencies at the mutation loci of LFNG, LENG8, NPHS1, HFE, ILDR1, and DMXL2 genes were analyzed in the 15 patients with severe periodontitis." (PMID 37435641, 2024).
scoliosis (1 paper, 2025). A congenital or acquired spinal deformity characterized by lateral curvature of the spine. "The genetic basis of congenital scoliosis is complex, involving mutations in multiple genes, particularly those related to the Notch signaling pathway, such as TBX6 and LFNG." (PMID 40980134, 2025).
viral infection (1 paper, 2022). "FAdVcirc_013009 and FAdVcirc_011337 target the gga-miR-7475-5p, which negatively correlated with CREBZF and LFNG during FAdV-4 infection, and these genes were all associated with the host cell response to viral infection." (PMID 35722302, 2022).
cancer (7 papers, 2016 to 2025). A tumor composed of atypical neoplastic, often pleomorphic cells that invade other tissues. "High expression of LFNG was found to be a risk factor for OS, DSS, and PFI in most cancer types, except for UCEC, KIRP, and ACC, where it acted as a protective factor." (PMID 37932706, 2023). "In conclusion, our pan-cancer analyses have revealed correlations between LFNG, MFNG, and RFNG expressions, with its methylation states, mutations, clinical prognosis, and immune cell infiltration." (PMID 37932706, 2023). "Fringe modulation of ligands will be of significance in understanding Notch activity in cancer stem cell asymmetric division where LFNG, DLL1 and NOTCH1 are present in the same cell." (PMID 29629872, 2018). "Most immune cells were negatively correlated with the expression of LFNG, MFNG, and RFNG in pan-cancers, especially T cells." (PMID 37932706, 2023). "GLI3, SMURF1, RBPJL, JAG1, LFNG and DTX2 were some of the most amplified genes present in at least 18 cancers." (PMID 31523055, 2019).
tumor (3 papers, 2020 to 2024). "Some studies have found that mutations in the LFNG gene are associated with resistance of tumor cells to chemotherapy drugs, which can lead to a diminished response to treatment and thus affect survival." (PMID 37932706, 2023). "Recent studies have found that mutations in the LFNG gene can cause tumor cells to reduce their ability to recognize by the immune cells, thereby evading detection by the immune system." (PMID 37932706, 2023). "In this study, LFNG is expressed at a high level in tumors, and its high level of transcriptional activity leads to its stronger regulatory effect on downstream NOTCH, which may lead to stronger invasion and migration ability of tumor cells." (PMID 37932706, 2023).
gastrointestinal system tumors (1 paper, 2023). "Given the similar expression pattern of the Finger family in gastrointestinal system tumors, we investigated the relationship between mutation and expression of LFNG, MFNG, and RFNG in LIHC, PAAD, and STAD." (PMID 37932706, 2023).
infection (1 paper, 2024). The state of being infected such as from the introduction of a foreign agent such as serum, vaccine, antigenic substance or organism. "Genes that overlapped with control-biased OCRs (regions with reduced accessibility due to MVA infection) included IL1R1, LFNG, and TTYH3 genes, all of which were downregulated in MVA-infected cells." (PMID 38862613, 2024).
skeletal dysplasia (1 paper, 2023). Any Mendelian diseases that affects growth and development of the skeleton. "Pathogenic variants in the LUNATIC FRINGE (LFNG) gene can cause spondylocostal dysostosis type-III (SCD3), which is a rare skeletal dysplasia characterized by the absence, fusion, or partial development of vertebrae and ribs." (PMID 40225152, 2023).
LFNG also shares sentences with these, for which no sentence is quoted: anemia (1 paper); aortic stenosis (1); autism (1); colon adenocarcinoma (1); colorectal adenocarcinoma (1); coronary artery disease (1); esophageal carcinoma (1); genetic disorder (1); hepatocellular carcinoma (1); pancreatic cancer (1); rectum adenocarcinoma (1); spondylothoracic dysostosis (1); testicular germ cell tumor (1); type 2 diabetes (1); uveal melanoma (1).